NDUFAF1 (NADH:ubiquinone oxidoreductase complex assembly factor 1)
Description:
As part of the MCIA complex, involved in the assembly of the mitochondrial complex I.
Synonyms: CIA30; CGI-65; CGI65; MC1DN11
Tractability: Small molecule: an approved drug acts on it. PROTAC: its protein half-life has been measured.
Gene: Protein-coding gene on chromosome 15 (41,387,218 to 41,409,403, reverse strand). Ensembl gene ENSG00000137806.
Subcellular location: Mitochondrion; Mitochondrion matrix
Subcellular location (Human Protein Atlas): Cytosol; Mitochondria
Pathways (Reactome):
Metabolism: Complex I biogenesis
Gene Ontology:
Molecular function: protein binding
Biological process: mitochondrial respiratory chain complex I assembly; mitochondrial electron transport, NADH to ubiquinone; protein-containing complex assembly
Cellular component: mitochondrial complex I intermediate assembly complex; mitochondrion; mitochondrial inner membrane; mitochondrial matrix
Genetic constraint (gnomAD): Loss-of-function variants: 14 observed, 26.03 expected, observed/expected ratio (o/e) 0.54, 90% interval 0.35 to 0.84. The upper end of that interval is the gene's LOEUF score, 0.84, which puts it in group 3 of 6, group 1 being the genes least tolerant of losing a copy. Missense variants: 372 observed, 385.24 expected, observed/expected ratio (o/e) 0.97, 90% interval 0.89 to 1.05. Synonymous variants: 104 observed, 135.59 expected, observed/expected ratio (o/e) 0.77, 90% interval 0.65 to 0.9.
Gene-disease validity (ClinGen):
ClinGen rates the evidence that NDUFAF1 causes each of these diseases.
mitochondrial disease (autosomal recessive): Moderate.
Homologues: Orthologues: chimpanzee NDUFAF1 (99% identical), macaque NDUFAF1 (93% identical), dog NDUFAF1 (84% identical), rabbit NDUFAF1 (81% identical), rat Ndufaf1 (80% identical), mouse Ndufaf1 (78% identical), guinea pig NDUFAF1 (75% identical), pig NDUFAF1 (70% identical), tropical clawed frog ndufaf1 (50% identical), zebrafish ndufaf1 (47% identical), Caenorhabditis elegans nuaf-1 (31% identical), Drosophila melanogaster CIA30 (30% identical).
Diseases named in the same sentence as NDUFAF1 in open-access papers:
NDUFAF1 is named in the same sentence as 24 diseases in open-access papers, as found by Europe PMC text mining. Sharing a sentence is not in itself a finding about the gene and the disease. The quoted sentences say what the papers report.
cardiomyopathy (2 papers, 2015 to 2021). A disease of the heart muscle or myocardium proper. "For example, we demonstrated that a previously well infant with overwhelming cardiomyopathy following respiratory syncytial virus infection had mutations in the NDUFAF1 gene encoding an assembly factor of complex I, a key enzyme of OXPHOS." (PMID 26122121, 2015). "However, mutations in another factor, ACAD9, which also associates with NDUFAF1 and ECSIT, appear to be a relatively common cause of complex I deficiency presenting as cardiomyopathy and/or exercise intolerance." (PMID 34032637, 2021).
pancreatic cancer (2 papers, 2015 to 2022). "The aberrant expression of NADH dehydrogenase 1 alpha subcomplex assembly factor 1 (NDUFAF1) caused mitochondrial respiration deficiency, which was correlated with the carcinogenesis of primary pancreatic cancer." (PMID 35535359, 2022). "We found that NDUFAF1 showed the most significant decrease after K-RasG12V induction and such decrease was also observed in clinical samples of pancreatic cancer tissues." (PMID 25714130, 2015). "Immunohistochemical analysis revealed that the majority 64% (51/80) of the pancreatic cancer tissues exhibited low expression of NDUFAF1." (PMID 25714130, 2015). "Overall, there was a statistically lower expression of NDUFAF1 in pancreatic carcinoma than in normal pancreatic tissues (P < 0.05, Fisher's exact test), suggesting that a decrease in NDUFAF1 expression may be clinically relevant in pancreatic cancer." (PMID 25714130, 2015). "Therefore, the decrease of NDUFAF1 observed in our model and pancreatic cancer specimen may indicate metabolic reprogramming driven by K-Ras oncogenic activation." (PMID 25714130, 2015).
septic shock (2 papers, 2021 to 2024). Shock caused by infection; frequently caused by gram negative bacteria, although some cases have been caused by other bacteria, viruses, fungi, and protozoa; characterized by fever, chills, tachycardia, tachypnea, and hypotension. "Expression levels of NDUFAF1 in two central nodes involved in epidermal growth factor (EGF) and Olfactomedin 4 (OLFM4) have been associated with acute kidney injury and septic shock." (PMID 38783263, 2024).
diabetes (1 paper, 2025). "For example, we found colocalisation between a UC risk locus and an eQTL for NDUFAF1 (PPh4 = 0.88), which encodes a mitochondrial complex I assembly factor targeted by metformin which is approved for treatment of diabetes." (PMID 40666361, 2025).
glaucoma (1 paper, 2012). Increased pressure in the eyeball due to obstruction of the outflow of aqueous humor. "Except for the NADH dehydrogenase (ubiquinone) 1 alpha subcomplex, assembly factor 1 (NDUFAF1), the UPR proteins altered in transgenic flies carrying these mutants are also altered in the human trabecular meshwork tissue, validating the fly system as a good genetic model of glaucoma." (PMID 22615763, 2012).
Hyperglycemia (1 paper, 2019). An increased concentration of glucose in the blood. "Tyrosol restored the expression of Ndufaf1, a member of complex I of electron transport chain under hyperglycemia." (PMID 31474865, 2019). "Indeed, tyrosol suppressed the level of mitochondrial ROS induced by hyperglycemia, most plausibly by restoring the expression level of Ndufaf1, a member of complex I of electron transport chain whose expression is disrupted in HO-1-/- mice." (PMID 31474865, 2019).
hypertrophic cardiomyopathy (1 paper, 2023). A condition in which the myocardium is hypertrophied without an obvious cause. "For example, mutations in NDUFAF1 are mostly associated with cardiological symptoms, including Wolff-Parkinson-White syndrome and hypertrophic cardiomyopathy." (PMID 36482121, 2023).
infantile hypertrophic cardiomyopathy (1 paper, 2024). "A missense variant in the NDUFAF1 subunit is linked to fatal infantile hypertrophic cardiomyopathy due to complex I mis‐assembly." (PMID 38546629, 2024).
leukodystrophy (1 paper, 2021). Leukodystrophies are a group of rare, progressive, metabolic, genetic diseases that affect the brain, spinal cord and often the peripheral nerves. "It is puzzling that the sequencing of case 1 only detected mutations in the NDUFAF1 gene (Case 1 was reported in 2013 {Wu L, Leukodystrophy associated with mitochondrial complex I deficiency due to a novel mutation in the NDUFAF1 gene." (PMID 34975718, 2021). "NDUFAF1 mutations are considered to be responsible for leukodystrophy." (PMID 34975718, 2021).
Mitochondrial encephalopathy (1 paper, 2021). "NDUFAF1 gene mutations are related to mitochondrial encephalopathy." (PMID 34975718, 2021).
Mitochondrial myopathy (1 paper, 2025). "This mitochondrial myopathy was partially explained by the decreased expression of complex I assembly factor Ndufaf1." (PMID 41178047, 2025).
Sepsis (1 paper, 2022). Sepsis is defined as life-threatening organ dysfunction caused by a dysregulated host response to infection. "Our study also found that NDUFAF1 expression was upregulated in patients with sepsis." (PMID 35345523, 2022).
cancer (2 papers, 2019 to 2020). A tumor composed of atypical neoplastic, often pleomorphic cells that invade other tissues. "However, it is unknown how the K-ras-driven cancer cells could maintain its homeostasis in mitochondrial energy metabolism with down-regulated NDUFAF1 that compromises the mitochondrial respiratory chain function." (PMID 31881642, 2019).
tumor (1 paper, 2015). "In addition, K-Ras expression caused a decrease in NDUFAF1 protein under hypoxia condition, which mimics the tumor microenvironment." (PMID 25714130, 2015).
NDUFAF1 also shares sentences with these, for which no sentence is quoted: Leigh syndrome (2 papers); acute kidney injury (1); Hepatic steatosis (1); Krabbe disease (1); Leukoencephalopathy (1); mitochondrial disease (1); respiratory syncytial virus infection (1); Sengers syndrome (1); thyroid cancer (1); Wolff-Parkinson-White syndrome (1).